ACTL6A (actin like 6A)
Diseases named in the same sentence as ACTL6A in open-access papers (continued):
Sharing a sentence is not in itself a finding about the gene and the disease.
colon carcinoma (5 papers, 2018 to 2023). "Next, we explored the association of the ACTL6A protein expression level with the clinicopathological features of 92 cases of colon cancer patients." (PMID 30348114, 2018). "In this study, we intend to explore the functional role of ACTL6A in colon cancer, elucidate its association with EMT, and finally exploit its potential clinical value." (PMID 30348114, 2018). "ACTL6A expression and its association with clinicopathologic features of colon cancer patients were also analyzed." (PMID 30348114, 2018). "These public databases results indicated that ACTL6A expression was upregulated in colon cancer tissue and indicated that ACTL6A might be act as an oncogenic role and associated progression of colon cancer, which was worthy of further study." (PMID 30348114, 2018). "Next, ACTL6A expression in colon cancer was also detected, which was consistent with the previous results that ACTL6A expression was higher in colon carcinoma than in normal colon tissue in Ki’s data and Kaiser’s data (P < 0.001, respectively)." (PMID 30348114, 2018). "In this study, we combined public databases and tissue samples from our center and found that ACTL6A expression levels in colon adenoma and cancer were both higher than that in normal colon, which first defined the expression pattern of ACTL6A in colon cancer." (PMID 30348114, 2018). "Next, we constructed ACTL6A knockdown SW620 (SW620ACTL6A-KD) and ACTL6A ectopic overexpression SW480 (SW480ACTL6A-OE) cell lines to study the functional role of ACTL6A in colon cancer cells in vitro." (PMID 30348114, 2018). "ACTL6A expression levels were analyzed in normal colon, colon adenoma and colon cancer specimens using public databases and tissue samples." (PMID 30348114, 2018). "Nonetheless, our study indicated that ACTL6A was a new potential target for clinical therapeutic research in colon cancer." (PMID 30348114, 2018). "Next, analysis of the clinicopathological characteristics of colon cancer patients showed that ACTL6A expression positively correlated with advanced pT status, distant metastasis, poor differentiation and microvascular/perineural invasion." (PMID 30348114, 2018). "Existing studies and our previous study have indicated that ACTL6A participated in the metastasis of some cancer; however, the role of ACTL6A in colon cancer remains to be defined." (PMID 30348114, 2018). "ACTL6A overexpression promoted migration and invasion of colon cancer cells, whereas ACTL6A knockdown exhibited the opposite effect in vitro." (PMID 30348114, 2018). "Next, cytological experiments further confirmed that ACTL6A promoted colon cancer cell migration and invasion in vitro." (PMID 30348114, 2018). "We further searched ACTL6A expression with the metastasis of colon cancer in Oncomine database, results showed ACTL6A expression in M1 stage or Dukes D stage group was higher than group without metastasis." (PMID 30348114, 2018). "The ACTL6A expression level in fresh colon cancer specimens was also higher than that in the corresponding adjacent normal colon specimens." (PMID 30348114, 2018). "We first explored ACTL6A expression in colon adenoma and colon cancer using the GEO database by searching “ACTL6A and colon cancer”." (PMID 30348114, 2018). "These assays indicated that ACTL6A overexpression promoted the migration capacity of colon cancer cells." (PMID 30348114, 2018). "Considering these results together, we suggest that ACTL6A might promote invasion and metastasis of colon cancer cells via inducing EMT." (PMID 30348114, 2018). "In this study we also found that ACTL6A promoted EMT in colon cancer cells." (PMID 30348114, 2018). "In the present study, we further explored the role of ACTL6A in colon cancer metastasis." (PMID 30348114, 2018). "Moreover, the ACTL6A protein expression in colon cancer was detected via immunochemistry in 92 cases of paraffin-embedded colon cancer tissues." (PMID 30348114, 2018).
colon carcinoma (continued). "ACTL6A may serve as a potential therapeutic target for colon cancer." (PMID 30348114, 2018). "Combined these results, the study indicated that ACTL6A overexpression promoted the migration and invasion capacity of colon cancer cells, and, thereby, could potentially promote the progression and metastasis of colon cancer." (PMID 30348114, 2018). "Moreover, we demonstrated that ACTL6A promoted EMT in colon cancer cells in vitro." (PMID 30348114, 2018). "In summary, our findings indicated that ACTL6A exhibited pro-tumor function and acted as an EMT activator in colon cancer." (PMID 30348114, 2018). "Our findings indicate that ACTL6A exhibits pro-tumor function and acts as an EMT activator in colon cancer." (PMID 30348114, 2018). "However, the role of ACTL6A in colon cancer is still unknown." (PMID 30348114, 2018). "Next, ACTL6A mRNA expression in 20 pairs of fresh colon cancer and noncancerous tissues from our center was detected via real-time PCR." (PMID 30348114, 2018). "Accordingly, transwell invasion assays also showed that more SW480 cells traversed the cell-permeable membrane with the ectopic overexpression of ACTL6A, while less SW620 cells traversed the membrane with ACTL6A knockdown, which indicated that ACTL6A promoted the invasiveness of colon cancer cells." (PMID 30348114, 2018). "ACTL6A-overexpression and ACTL6A-knockdown colon cancer cells were used to perform cytological experiments to explore the potential biological function of ACTL6A in metastasis and EMT in colon cancer." (PMID 30348114, 2018). "Because our previous study has found that ACTL6A can induce EMT in HCC, we further explored whether ACTL6A could induce EMT in colon cancer cells." (PMID 30348114, 2018). "In the present meaningful work, we found that ACTL6A expression was upregulated in colon cancer, its expression correlated with adverse clinicopathological features of colon cancer patients, and its overexpression promoted migration, invasion and EMT in colon cancer cells." (PMID 30348114, 2018). "Seventeen pairs of cancer and noncancerous tissues from surgically resected colon cancer were analyzed in another GEO database GDS 4382; the results showed that the ACTL6A signal intensity in the cancer tissue was significantly higher than that in the paired noncancerous tissue (p < 0.001)." (PMID 30348114, 2018). "However, the exact regulatory mechanism of ACTL6A in promoting metastasis and EMT in colon cancer is still not fully studied; therefore, further studies are urgently needed in future." (PMID 30348114, 2018).
osteosarcoma (4 papers, 2019 to 2021). A usually aggressive malignant bone-forming mesenchymal neoplasm, predominantly affecting adolescents and young adults. "Moreover, ACTL6A maintains the stem-like phenotype in keratinocytes, stimulates neural progenitor cell proliferation, enhances the osteosarcoma and hepatocellular carcinoma cell cancer phenotype, and drives an aggressive epidermal squamous cell carcinoma phenotype." (PMID 34689163, 2021).
breast carcinoma (3 papers, 2021 to 2025). "We then analyzed the correlation between ACTL6A expression and the clinicopathological characteristics of patients with breast cancer and found that high ACTL6A levels were associated with T, N classification and the Ki-67 index." (PMID 33541412, 2021). "Collectively, CDK inhibitors are reported not to be suitable for all patients, however, our results uncover the crucial role of ACTL6A in identifying a subset of breast cancer patients who would benefit from therapy with K03861." (PMID 33541412, 2021). "However, whether ACTL6A takes part in the tumorigenesis of breast cancer, especially TNBC, remains unclear." (PMID 33541412, 2021). "To explore the role of ACTL6A/MYC/CDK2 in the progression of TNBC, we detected these genes in breast cancer tissues and cell lines." (PMID 33541412, 2021). "Moreover, we analyzed the mRNA expression of ACTL6A and CDK2, the protein expression of MYC in public human breast cancer datasets from TCGA." (PMID 33541412, 2021). "The clinical significance of high ACTL6A expression was further assessed using immunohistochemistry (IHC) staining in 344 archived breast cancer tissue samples, including 124 non-TNBC cases and 220 TNBC cases." (PMID 33541412, 2021). "Given the mechanism that ACTL6A activated the MYC/ CDK2 axis, we hypothesized that a CDK2 inhibitor would have potentially therapeutic effects against TNBC in combination with the first-line chemotherapy drug of breast cancer, paclitaxel (PTX)." (PMID 33541412, 2021).
colorectal cancer (3 papers, 2022 to 2025). A primary or metastatic malignant neoplasm that affects the colon or rectum. "Additional multivariate analysis showed that ACTR6/ACTL6A may function as separate risk variables for the prognosis of patients with colorectal cancer." (PMID 40130245, 2025). "ACTL6A, a subunit of the SWI/SNF and INO80 chromatin remodeling complexes, is frequently overexpressed in various cancers, and its depletion attenuates cell proliferation in colorectal cancer (CRC)." (PMID 40877226, 2025).
pancreatic cancer (3 papers, 2016 to 2025). "Gene essentiality data further boosts the importance of dbEM in cancer research e.g. ACTL6A gene has high negative GARP score (-2.4) in case of pancreatic cancer cell line, HPDE." (PMID 26777304, 2016). "Analysis of The Cancer Genome Atlas (TCGA) datasets revealed that high expression of RCC1 or ACTL6A was significantly correlated with poor survival of pancreatic cancer patients (p < 0.05), whereas RUVBL2 expression was not correlated with the patient survival (p = 0.4524)." (PMID 41391757, 2025).
rhabdomyosarcoma (3 papers, 2017 to 2020). A rare aggressive malignant mesenchymal neoplasm arising from skeletal muscle. "High expression of BAF53a blocks myogenic differentiation and promotes cell proliferation in rhabdomyosarcoma, suggesting that ACTL6A/BAF53a is implicated in cancer development." (PMID 32447427, 2020). "The study in rhabdomyosarcoma demonstrated miR-206 was the upstream of ACTL6A, and miR-206 was identified to regulate EMT via PI3k/Akt/mTOR signaling, which was also the classical EMT related signaling." (PMID 30348114, 2018).
esophageal squamous cell carcinoma (2 papers, 2019 to 2025). Esophageal squamous cell carcinoma (ESCC) is a type of esophageal carcinoma (EC) that can affect any part of the esophagus, but is usually located in the upper or middle third. "Knockdown of ACTL6A can inhibit the activity of this pathway, thereby increasing the radiosensitivity of esophageal squamous cell carcinoma." (PMID 41137713, 2025). "The protein expression level of ACTL6A in tumor tissue samples of clinical esophageal squamous cell carcinoma patients was analyzed by immunohistochemistry, and it was found that the prognosis of the high expression group was worse than that of the low expression group." (PMID 41137713, 2025). "ACTL6A may become an important therapeutic target for esophageal squamous cell carcinoma, providing a necessary theoretical basis for future treatment strategies." (PMID 41137713, 2025). "Whether SOX2 and ACTL6A/TP63 interact with the Hippo‐YAP1 pathway in esophageal squamous cell carcinoma (ESCC) remains unclear." (PMID 31560173, 2019).
lung squamous cell carcinoma (2 papers, 2014 to 2019). "Vulnerability of cancer cells to ACTL6A or FXR1 knock-out would be necessary to characterize the role of these genes in lung squamous cell carcinoma." (PMID 25484917, 2014).
melanoma (2 papers, 2021 to 2025). A malignant, usually aggressive tumor composed of atypical, neoplastic melanocytes. "Interestingly, the expression patterns of BRG1/ACTL6A and loricrin were completely different in melanoma, another type of skin tumour derived from melanocytes, confirming a tumour-specific regulatory function of uc.291 and BRG1 in keratinocyte-derived malignancies." (PMID 35201472, 2021).
aplastic anemia (1 paper, 2025). Anemia resulting from bone marrow failure (aplastic or hypoplastic bone marrow). "The conditional knockout (cKO) of BAF53A/ACTL6A in HSCs led to mice experiencing bone marrow failure, aplastic anemia, and death." (PMID 41227365, 2025).
breast tumors (1 paper, 2021). "Analyses of human breast tumors indicate that SOX4 mRNA is uniformly overexpressed in basal-like tumors relative to adjacent normal tissue along with the SWI/SNF catalytic subunit SMARCA4 and SMARCB1 SMARCC1, SMARCD2, and ACTL6A, which encode for the essential subunits of this complex." (PMID 33837205, 2021).
colon adenocarcinoma (1 paper, 2025). "The Cancer Genome Atlas (TCGA) colon adenocarcinoma (COAD) data were analyzed to explore the transcription of ACTL6A in CRC." (PMID 40877226, 2025).
colon adenoma (1 paper, 2018). An adenoma that arises from the colon. "Results showed that the ACTL6A expression in colon adenoma was significantly higher than that in normal mucosa (p < 0.001)." (PMID 30348114, 2018). "The data from both the Gene Expression Omnibus (GEO) and Oncomine databases showed that ACTL6A expression levels in colon adenoma and cancer were higher than those in normal colon samples." (PMID 30348114, 2018). "Next, we also detected ACTL6A mRNA expression in the Oncomine database and found that ACTL6A expression in colon adenoma was significantly higher than that in normal colon according to Sabates-Bellver’s data and Skrzypczak’s data (P < 0.001, respectively)." (PMID 30348114, 2018).
endometriosis (1 paper, 2022). The growth of functional endometrial tissue in anatomic sites outside the uterine body. "Most notably, ARID1A in endometriosis-related OC, SMARCA4, and SMARCB1 in hypercalcemic type small cell ovarian carcinoma (SCCOHT), ACTL6A, CHRAC1, RSF1 amplification in high-grade serous OC." (PMID 36430148, 2022).
heart-hand syndrome (1 paper, 2021). Heart-hand syndrome refers to a group of congenital disorders characterized by malformations of the upper limbs and heart. "Thus, mutation analysis of the ACTL6A gene should be considered in patients with BAF-opathies or heart-hand syndromes due to potential misdiagnosis." (PMID 34485408, 2021).
Intellectual disability (1 paper, 2025). "Intellectual disability is linked to heterozygous variations in BAF53A/ACTL6A." (PMID 41227365, 2025).
leukemia (1 paper, 2021). A malignant (clonal) hematologic disorder, involving hematopoietic stem cells and characterized by the presence of primitive or atypical myeloid or lymphoid cells in the bone marrow and the blood.
liver cancer (1 paper, 2019). An epithelial or non-epithelial malignant neoplasm that arises from the liver. "ACTL6A has a protumorigenic function and its expression level correlated with worse clinicopathological features in liver cancer and in colon cancer." (PMID 31769422, 2019). "Mechanistically, ACTL6A overexpression promoted migration and invasion and induced EMT in vitro and promoted tumor growth and metastasis in a mouse liver cancer xenograft model." (PMID 31769422, 2019).
major depressive disorder (1 paper, 2025). An episode of depression lasting two or more weeks without an intervening episode of mania. "Moreover, Actl6a has been implicated in autophagy and immune responses, such as in major depressive disorder, where it affects mitochondrial autophagy and immune infiltration." (PMID 39875055, 2025).
malignant rhabdoid tumors (1 paper, 2025). "In malignant rhabdoid tumors (MRTs), aberrant co-expression of ACTL6A and ACTL6B is observed, accompanied by altered DNA methylation at differentiation-associated genes and at the neuronal marker NeuN." (PMID 41514521, 2025).
medulloblastoma (1 paper, 2020). A malignant, invasive embryonal neoplasm arising from the cerebellum. "The roles of ACTL6A, EIF4A3, ENAH, and UMPS in medulloblastoma had not been reported." (PMID 33101383, 2020).
mesothelioma (1 paper, 2021). A usually malignant and aggressive neoplasm of the mesothelium which is often associated with exposure to asbestos. "We show that transient ACTL6A knockdown or stable knockout reduces mesothelioma cell proliferation, spheroid formation, invasion, and migration." (PMID 34689163, 2021). "We next examined the role of ACTL6A and p21Cip1 in regulating the cancer phenotype in another mesothelioma cell line, NCI-Meso-17 cells." (PMID 34689163, 2021). "We are interested in the role of ACTL6A in mesothelioma, as YAP1/TAZ function is required for optimal mesothelioma cancer cell survival." (PMID 34689163, 2021).
orofacial cleft (1 paper, 2022). A disorder of facial skeleton that is characterized by cleft lip and/or cleft palate that result in feeding, speech and hearing problems caused by failures during development. "The protein-truncating DNMs were found in ACTL6A, ARHGAP10, MINK1, TMEM5 and TTN genes, all of which are loci with substantial annotation, functional and/or animal model data supporting their roles in orofacial clefts." (PMID 35817949, 2022).
ovarian tumors (1 paper, 2023). "Elevated expression of ACTL6A is associated with cancer stem cell-like features, advanced stages of ovarian tumors and poor survival of patients." (PMID 36768349, 2023). "The results showed that 11 of 11 malignant ovarian tumors displayed moderate to strong nuclear, cytoplasmic, and membrane immunoreactivity positivity of ACTL6A protein." (PMID 36768349, 2023).
ovary adenocarcinoma (1 paper, 2023). "We operated cross-associations between drug response and ACTL6A expression in 30 ovary adenocarcinoma cell lines." (PMID 36768349, 2023).
psoriasis (1 paper, 2023). An autoimmune condition characterized by red, well-delineated plaques with silvery scales that are usually on the extensor surfaces and scalp. "In the present work, we explore the role of uc.291 and its interactor ACTL6A in psoriasis skin, using quantitative real-time PCR (RT-qPCR), immunohistochemistry and bioinformatic analysis of publicly available datasets." (PMID 38041107, 2023). "Given that impaired differentiation of keratinocytes occurs in psoriasis, we decided to focus our attention on the involvement of uc.291 and its interactor ACTL6a in this patology." (PMID 38041107, 2023). "To support our hypothesis on the involvement of uc.291 and its competitor ACTL6A in modulating keratinocyte differentiation, we decided to establish an in vitro model of psoriasis by treating differentiated cells with IL-22." (PMID 38041107, 2023). "Furthermore, we provide evidence that the expression of uc.291, FLG and LOR is reduced, while ACTL6A mRNA is up-regulated, in an in vitro psoriasis-like model obtained by treating differentiated keratinocytes with interleukin 22 (IL-22)." (PMID 38041107, 2023). "Since lncRNA uc.291 can dislodge ACTL6A-chromatin binding on the EDC locus, allowing the activation of transcription of differentiation genes residing at the EDC locus, including filaggrin and loricrin, we decided to determine their expression in patients with psoriasis skin and in healthy donors." (PMID 38041107, 2023).
schizophrenia (1 paper, 2015). A major psychotic disorder characterized by abnormalities in the perception or expression of reality. "The highest three scoring genes have all been previously shown to play important roles in the brain: ACTL6A, a chromatin remodeling factor which is required for the development of neural progenitors; VRK2, a gene implicated in schizophrenia; and the Huntington’s gene, HTT." (PMID 25970446, 2015).
spinal cord injury (1 paper, 2025). Penetrating and non-penetrating injuries to the spinal cord resulting from traumatic external forces (e.g., WOUNDS, GUNSHOT; WHIPLASH INJURIES; etc.). "This study explored the role of Actl6a in spinal cord injury (SCI), focusing on how it promotes cell survival by regulating autophagy." (PMID 39875055, 2025).